STAT3 (signal transducer and activator of transcription 3)
Diseases named in the same sentence as STAT3 in open-access papers (continued):
Sharing a sentence is not in itself a finding about the gene and the disease.
thyroid cancer (continued). "There is a strong correlation between STAT3 overexpression and the pathogenesis of thyroid cancer, as the dysregulated activation of STAT3 has been reported in human specimens of thyroid cancers." (PMID 31936675, 2020). "Caspases are the main executers of apoptosis and are activated by upstream signaling (such as STAT3), as has been reported for different human malignancies such as breast, blood, and thyroid cancers." (PMID 31936675, 2020). "SIX1, a tumor promoter, promoted the proliferation and invasion of thyroid carcinoma via activation of STAT3 signaling and its downstream targets in an EYA1‐dependent manner." (PMID 32851683, 2020). "Our previous study also showed that CDK5 regulates thyroid cancer cell proliferation through the activation of STAT3 on Ser-727 phosphorylation." (PMID 31395805, 2019). "We previously found that CDK5 is responsible for thyroid cancer growth through signal transducer and activator of transcription 3 (STAT3) activation." (PMID 31395805, 2019). "The present findings provide evidence that LDR-induced PAX8 acts as an important regulator for suppression of thyroid carcinogenesis through novel STAT3/miR-330-5p pathway in thyroid cancers." (PMID 30760304, 2019). "Our data indicated LDR effectively recovered TSHR levels in thyroid carcinoma cells, perhaps decreasing STAT3-miRNA axis route accounting for the high undifferentiated phenotype." (PMID 30760304, 2019). "The role of STAT3 in thyroid cancer tumorigenesis is still inconclusive, indicating that the underlying mechanism should be investigated in the future." (PMID 29515111, 2018). "Among them, STAT3 has been studied in many cancer types, but its role in thyroid cancer is still debated." (PMID 29125844, 2017). "The MAPK/Erk, PI3K/Akt, STAT3, and the Wnt/βcatenin pathways were selected for assessment due to their well-documented link to thyroid cancer development and progression." (PMID 27845909, 2016). "In summary, the biological effects of JAK/STAT3 on thyroid cancer are very complicated; further studies are needed to clarify the associations between JAK/STAT3 pathway and thyroid cancer to help develop novel drugs for targeted therapy." (PMID 26985248, 2016). "Leptin promoted thyroid cancer progression is associated with the Janus kinase 2 (JAK)-signaling transducer and activator of transcription (STAT)-3 signaling pathway and with STAT3 target gene expression." (PMID 27050378, 2016). "This is further supported by work in tumor cell lines showing that STAT3 is a negative regulator of tumor growth in certain cancers such as thyroid carcinoma." (PMID 26272737, 2015). "Increased expression and activation of STAT3 is detected in the tissue specimens of thyroid cancers, including lymphatic metastasis of PTC." (PMID 24662939, 2014). "STAT3 therefore has opposing effects on tumorigenesis, and these paradoxical STAT3 effects are also observed in certain thyroid cancer types." (PMID 24662939, 2014). "Of note, while STAT3 played a role as a transcription factor in both thyroid cancer types, the role of STAT3 in the mitochondria was also important to mediate tumor suppressive signaling in PTC." (PMID 24662939, 2014). "Furthermore, through examination of the expression of JAK1, p-JAK1, JAK2, p-JAK2, STAT3, and p-STAT3 in diverse thyroid cancer cell lines, it was discovered that ATC cells exhibit elevated levels of background expression." (PMID 38336839, 2024). "Inflammatory pathways like STAT3 may also contribute, as evidenced by elevated STAT3 activity in both BC and thyroid carcinoma patients." (PMID 39469634, 2024). "In thyroid cancer, this protein has been reported as a potential diagnostic and prognostic biomarker of PTC by regulating epithelial-mesenchymal transition and activating the IL-6/JAK2/STAT3 pathway." (PMID 37833989, 2023).
thyroid cancer (continued). "Similarly, in lung cancer, the overexpression of ANXA8 activates the EGFR/AKT/mTOR signalling pathway to promote proliferation, while in thyroid cancer, increased ANXA1 promotes thyroid cancer proliferation by mediating IL-6/JAK2/STAT3." (PMID 36936694, 2023). "Mutations in EYA1 may cause dysregulation and act as a tumor promoter with SIX1 via activation of STAT3 signaling in thyroid carcinomas." (PMID 38067373, 2023). "In addition, an inhibitor of STAT3 was able to inhibit the proliferation of HFD-induced thyroid cancer cells through the reduction of cyclins D1 and B1, CDK4, CDK6 and pRB." (PMID 36060941, 2022). "It has been found that BRAF inhibitors (vemurafenib) may lead to JAK2/STAT3 signaling activation in BRAF mutant thyroid cancer cell lines." (PMID 36430869, 2022). "Thus, it is impossible to further evaluate the influence of STAT3 protein on the prognosis of patients with thyroid cancer." (PMID 35463085, 2022). "Also, STAT3 expression increases in thyroid cancer tissue with the metastasis of thyroid cancer lymph nodes or an increase in TNM staging, which subsequently promotes the occurrence and development of thyroid cancer." (PMID 35463085, 2022). "Taken together, these data strongly suggested that oridonin could suppress VEGFA expression via JAK2/STAT3 pathway in thyroid cancer cells." (PMID 35813296, 2022). "Interestingly, oridonin effectively repressed p-JAK2 and p-STAT3 protein levels in thyroid cancer TPC-1 and BCPAP cell lines in a concentration-dependent manner." (PMID 35813296, 2022). "We found that overexpression of JAK2 could partially reverse the change of p-STAT3, E-cadherin and N-cadherin protein levels induced by oridonin in thyroid cancer TPC-1 and BCPAP cells." (PMID 35813296, 2022). "Thus, the expression of STAT3 protein has reference significance for the early diagnosis, treatment, and prevention of thyroid cancer." (PMID 35463085, 2022). "TFF3 inhibits thyroid cancer cell progression related to IL-6/JAK/STAT3 signaling pathway." (PMID 34567204, 2021). "LINC00671 or STAT3 activation may be useful for treatment of thyroid cancer with LDHA overexpression." (PMID 34404767, 2021). "The IL-6/JAK/STAT3 signaling pathway might be involved in the effect of TFF3 on thyroid cancer cell progression." (PMID 34567204, 2021). "Moreover, in thyroid cancer samples, STAT3 or LINC00671 expression is negatively correlated with LDHA expression as well as increased tumor FDG uptake." (PMID 34404767, 2021). "Studies have shown that the expression level of STAT3 in normal thyroid tissue, thyroid adenoma, and thyroid cancer sequentially increases, suggesting that the increase in STAT3 expression level is closely related to the occurrence of thyroid cancer." (PMID 34567204, 2021). "Inhibition of LDHA or STAT3 or supplement of LINC00671 could be potential therapeutic strategies in thyroid cancer." (PMID 34404767, 2021). "Then, STAT3-activated M2 macrophages overexpressing IL-6 would promote thyroid cancer progression." (PMID 34638305, 2021). "The role of STAT3 in thyroid malignancies is relatively less studied, however, there are data from some in vitro as well as in vivo studies, including the recent investigations on how STAT3 plays a critical role in noncoding RNA-mediated alterations related to the thyroid cancer pathogenesis." (PMID 32182833, 2020). "By contrast, IL6/STAT3 axis mediated resistance to BRAF inhibitors in thyroid carcinoma cells." (PMID 32851683, 2020). "Another lncRNA known as papillary thyroid carcinoma susceptibility candidate 3 (PTCSC3) associated with ATC progression and doxorubicin resistance by targeting signal transducer and activator of transcription 3 (STAT3) protein." (PMID 33126409, 2020).
thyroid cancer (continued). "In summary, these data suggest that nevirapine has inhibitory effects in human dedifferentiated thyroid cancer by targeting the IL‐6/STAT3 signaling pathway, and our findings demonstrate that nevirapine may be useful as a therapy against human thyroid cancer." (PMID 31631580, 2019). "We finally wanted to investigate how LDR can suppress STAT3 activation in thyroid cancer cells." (PMID 30760304, 2019). "Besides, SIX1 promoted the proliferation and invasion of thyroid carcinoma via activation of STAT3 signaling and its downstream targets in an EYA1-dependent manner." (PMID 31921695, 2019). "STAT3 could thus promote the effects of obesity induced by high-fat diet on the development and progression of thyroid cancer in Thrb(PV/PV)Pten(+/-) mice." (PMID 26985248, 2016). "For example, STAT3 was found as a negative regulator of thyroid cancer since it could activate transcription of the tumor suppressor insulin-like growth factor binding protein 7 (IGFBP7), and negatively regulate aerobic glycolysis." (PMID 27577070, 2016). "However, STAT3 expression was found in 11 of the 35 (31%) thyroid cancer tissues; pSTAT3 expression was found in only three of the 35 (9%) benign tissues, but in 40 of the 41 (98%) of the cancer tissues." (PMID 26985248, 2016). "In addition to these mechanisms, STAT3 in thyroid cancer appears to be regulated via an unexpected mechanism." (PMID 24662939, 2014). "In this review, we provide an update of STAT3 function in thyroid cancer and discuss some of the evidences that support this hypothesis." (PMID 24662939, 2014). "However, the role of the Janus kinase (JAK)/signal transducer and activator of transcription (STAT3) pathway, a well-known mediator of tumorigenesis in different tumor types, is relatively less understood in thyroid cancer." (PMID 24662939, 2014). "Notably, STAT3 deficiency resulted in larger and more proliferative tumors, suggesting that STAT3 may function as a negative regulator of tumor growth, at least in the context of thyroid cancer." (PMID 40620232, 2025). "Thus, we hypothesized JAK2/STAT3 signaling pathway participated in the anti-migratory and anti-invasive effects of oridonin on thyroid cancer cells." (PMID 35813296, 2022). "However, it remains to be explored whether the STAT3 negative regulation of thyroid cancer applies to all histological subtypes, thyroid cancer staging, and distant metastasis progression." (PMID 35463085, 2022). "In thyroid cancer, the JAK2/STAT3 signaling pathway not only directly induces the EMT process and enhances cancer cell migration but also synergistically promotes VEGF-A secretion, thereby regulating tumor metastasis and angiogenesis." (PMID 40530008, 2025). "Metformin shows potential therapeutic value by inhibiting the mTOR signaling pathway and targeting JAK2 in the JAK2/STAT3 signaling pathway, thereby effectively inhibiting the proliferation, migration, and EMT of thyroid cancer cell lines." (PMID 40530008, 2025). "In thyroid cancer, low expression of TFF3 can increase cell proliferation, migration, and invasion via activation of the IL-6/JAK/STAT3 signaling pathway." (PMID 38745021, 2024). "Our studies revealed that oridonin inhibited metastatic phenotype, angiogenesis and modulated EMT in thyroid cancer in vitro and vivo through downregulation of JAK2/STAT3 signaling pathway." (PMID 35813296, 2022). "Therefore, we hypothesize that STAT3 may be one of the oncogenes of thyroid cancer." (PMID 35463085, 2022). "Our research identified a novel STAT3/LINC00671/LDHA axis to regulate glycolysis, growth, and metastasis of thyroid cancer." (PMID 34404767, 2021). "It has been reported that miR−148a reduces thyroid cancer cell proliferation by PI3K/AKT and STAT3 signaling." (PMID 34290668, 2021). "In thyroid cancer patients, LINC00671 expression is negatively correlated with LDHA and STAT3 expression." (PMID 34404767, 2021).
thyroid cancer (continued). "It was also found that the POU4F1 suppressed tumor metastasis via c-MET/STAT3 inhibition and EMT suppression in thyroid cancer." (PMID 34970597, 2021). "On the other hand, our previous study demonstrated that CDK5 inhibition reduced tumor formation with phosphorylation of STAT3 on Ser-727, and it has been reported that Her2 is an upstream protein of CDK5 in thyroid carcinoma cells." (PMID 31395805, 2019). "Despite the plethora of information on different signal transduction pathways in thyroid cancer, the information on the Janus kinase (JAK)/signal transducer and activator of transcription (STAT3) pathway is relatively limited." (PMID 24662939, 2014). "We investigated the effects of AZD1480 on IL-6/JAK and RET- dependent signaling (STAT3, ERK/MAPK and PI3K/AKT) as well as its biological effects in human thyroid cancer models (cell lines and a xenograft model)." (PMID 23056499, 2012). "This inhibitor led to growth inhibition and/or apoptosis of the thyroid cancer cell lines in vitro, as well as to tumor regression of TPC-1 xenografts, where it efficiently blocked STAT3 activation in tumor and stromal cells." (PMID 23056499, 2012). "Dong quai methylin downregulates the JAK2/STAT3 signaling pathway, thereby inhibiting VEGF-A expression to limit angiogenesis and directly reversing the EMT phenotype, which in turn suppresses thyroid cancer migration." (PMID 40530008, 2025). "Regarding the relationship between STAT3 and thyroid cancer, existing research has failed to reach a consensus." (PMID 35463085, 2022). "The study also found that the expression level of STAT3 in cases with lymph node metastasis was uncommonly higher than that in the group without lymph node metastasis, and the higher the stage of thyroid cancer, the higher the positive rate of STAT3." (PMID 34567204, 2021). "In thyroid carcinoma, LINC00511 could interact with TAF1 to upregulate JAK2, which then activated STAT3 signaling pathways to maintain the resistance to radiotherapy of malignant cells." (PMID 32713253, 2020). "Intriguingly, recent studies have demonstrated that, in thyroid cancer, the JAK/STAT3 pathway may function in the context of tumor suppression rather than promoting tumorigenesis." (PMID 24662939, 2014). "In conclusion, AZD1480 effectively blocks proliferation and tumor growth of activated RET- thyroid cancer cell lines, likely through direct RET inhibition in cancer cells as well as by modulation of the microenvironment (e.g. via JAK/phospho-STAT3 inhibition in endothelial cells)." (PMID 23056499, 2012). "To further confirm whether JAK2/STAT3 pathway is involved with anti-metastatic characteristic of oridonin in human thyroid cancer cells or not, we overexpressed JAK2 by transiently transfecting JAK2 plasmid." (PMID 35813296, 2022). "Hence, we investigated whether curcumin, a natural compound, can target the JAK/STAT3 signaling pathway to induce cytotoxic effects in papillary thyroid cancer (PTC) cell lines (BCPAP and TPC-1) and derived thyroid cancer stem-like cells (thyrospheres)." (PMID 31936675, 2020). "However, our findings show a small and stable decrease in the relative expression of STAT3 in thyroid cancer cells treated with 15d-PGJ2, although not significant." (PMID 27190500, 2016). "Their research has also suggested that JAK/STAT3 pathway could only inhibit but not promote thyroid cancer." (PMID 26985248, 2016). "Intriguingly, emerging evidences suggest that the JAK/STAT3 pathway may have tumor suppressive effects on thyroid cancers, unlike its effects on many other cancer types." (PMID 24662939, 2014). "Conversely, REX1 significantly enhances EMT-dependent migration by activating the JAK2/STAT3 signaling pathway and may indirectly promote the formation of a pro-angiogenic microenvironment, further confirming the synergistic role of EMT and angiogenesis in thyroid cancer." (PMID 40530008, 2025).
thyroid cancer (continued). "The detailed mechanism of inhibiting migration and invasion by nevirapine in dedifferentiated thyroid cancer cells was not performed in our study, but the next part of our work will be to explore in depth how nevirapine works to inhibit migration and invasion by IL‐3/STAT3 pathway." (PMID 31631580, 2019). "Although these effects were independent of STAT3 in thyroid cancer cells, AZD1480 effectively inhibited phospho-STAT3 in the stroma, particularly in endothelial cells." (PMID 23056499, 2012). "Thus, our data suggested that although JAK/STAT3 signaling could be upregulated by TME stromal cells and could influence CSC behaviors, targeting the signaling will be unlikely to be beneficial to thyroid cancer patients." (PMID 36982542, 2023). "However, the opposite conclusion had been obtained by other researchers that STAT3 might be a negative regulator of thyroid tumor growth, so the JAK-STAT3 pathway was important for inhibiting the procession of thyroid cancer rather than promoting it." (PMID 37660003, 2023).